GFAP (glial fibrillary acidic protein)
Diseases named in the same sentence as GFAP in open-access papers (continued):
Sharing a sentence is not in itself a finding about the gene and the disease.
fibromyalgia (3 papers, 2024 to 2025). A chronic disorder of unknown etiology characterized by pain, stiffness, and tenderness in the muscles of neck, shoulders, back, hips, arms, and legs. "The accumulation of Iba1-positive microglia and GFAP-positive astrocytes was found in the thalamus of the ICS-induced fibromyalgia mice (Tukey’s test, * p < 0.05, n = 6)." (PMID 41008336, 2025). "The ICS-induced fibromyalgia mice exhibited an increase in the number of microglia and astrocytes labeled with Iba1 and GFAP compared to the normal mice (Tukey’s test, * p < 0.05, n = 6)." (PMID 41008336, 2025). "We detected a noteworthy increase in GFAP and Iba1 expression in the ICS-induced fibromyalgia pain mice (Tukey’s test, * p < 0.05, n = 6)." (PMID 41008336, 2025). "Both the GFAP and Iba1 expression levels were elevated in the PAG of fibromyalgia model mice (* p < 0.05, n = 6), but in contrast to the DRG, these responses were depleted by both acupoint and the ICV injection of AEA (i.e., both acupoint and ICV injection recapitulated the effects of EA)." (PMID 41007675, 2025).
fibrosis (3 papers, 2014 to 2023). the formation of excess fibrous connective tissue in an organ or tissue in a reparative or reactive process. "According to some researchers, GFAP development in the liver is associated with hepatic fibrosis and inflammatory cellular invasion, since stimulated HSC release cytokines which drive inflammatory cells." (PMID 36282381, 2023). "In CCl4-induced mouse fibrosis, GFAP-Cre;Bsgfl/fl mice showed less hepatic inflammatory infiltration and serum CXCL1 expression." (PMID 29642635, 2018). "Fibrosis in PDGF-C transgenic mice, as demonstrated by staining and hydroxyproline content, is preceded by activation and proliferation of hepatic stellate cells, as shown by collagen, α-smooth muscle actin and glial fibrillary acidic protein staining." (PMID 24710173, 2014).
Glucose intolerance (3 papers, 2017 to 2024). Glucose intolerance (GI) can be defined as dysglycemia that comprises both prediabetes and diabetes. "HF diet resulted in the greatest weight gain, adiposity, and glucose intolerance in 3xTg-AD females, which were associated with markedly increased hypothalamic expression of GFAP and IL-1β, as well as GFAP labeling in several hypothalamic nuclei that regulate energy balance." (PMID 32993686, 2020). "High-fat diets resulted in the greatest weight gain, adiposity, and glucose intolerance in 3xTg-AD females, accompanied by a significant increase in hypothalamic expression of glial fibrillary acidic protein (GFAP) and interleukin-1β (IL-1β)." (PMID 39272160, 2024).
heart failure (3 papers, 2023 to 2024). Inability of the heart to pump blood at an adequate rate to meet tissue metabolic requirements. "That study, conducted among patients with heart failure, reported former smokers had lower GFAP levels." (PMID 38204926, 2024).
infectious colitis (3 papers, 2011 to 2024). A viral or bacterial infectious process affecting the large intestine. "Although GDNF - anti-apoptic agent for epithelial cells- and GFAP is increased in the inflamed gut of CD, it is significantly less than in the inflamed intestines of UC patients or patients with infectious colitis." (PMID 21235736, 2011). "The biopsies of patients with infectious colitis (Clostridium difficile) was characterized by a impressive increase of GFAP- and GDNF-positive structures similar to the inflamed gut biopsies of patients with UC." (PMID 21235736, 2011). "GFAP and GDNF as signs of activated EGCs are increased in the inflamed mucosa of patients with UC and infectious colitis, which underline an unspecific role of EGC in the regulation of intestinal inflammation." (PMID 21235736, 2011). "The GFAP expression of the inflamed intestines in patients with infectious colitis showed nearly the same impressive GFAP content, about 4-fold in comparison to control, like gut inflammation in patients with UC." (PMID 21235736, 2011). "The expression of glial fibrillary acidic protein (GFAP) in colonic biopsies of patients with IBD, controls and patients with infectious colitis was detected by immunohistochemistry and Western blot." (PMID 21235736, 2011). "Therefore we investigated the GFAP content as marker for EGCs in the inflamed and non-inflamed intestines of patients with CD and UC in comparison to controls and patients with infectious colitis and postulate a diminished EGC network with reduced GDNF content in the intestines of patients with CD." (PMID 21235736, 2011). "Here we determined the distribution of GFAP-positive EGCs and GDNF in the inflamed and non-inflamed colon of patients with CD, UC and infectious colitis." (PMID 21235736, 2011).
intracranial hypertension (3 papers, 2023 to 2024). A finding characterized by increased cerebrospinal fluid pressure within the skull. "Intracranial hypertension can also lead to optic disc edema and optic nerve sheath edema.It is also possible that these alterations result from an autoimmune reaction against GFAP, which is expressed in the retina by astrocytes and Müller cells, particularly in the peripapillary region." (PMID 38585352, 2024). "Indeed, this cranial nerve is known to be highly sensitive to increased intracranial pressure, and intracranial hypertension is described in patients with CSF GFAP-Abs." (PMID 37540278, 2023).
liver disease (3 papers, 2015 to 2025). "Peripheral blood analysis showed significant changes in neurodegeneration markers (NfL, Aβ, p-tau, t-tau, GFAP, MOG) and bile acid profiles, reinforcing the systemic nature of neuroinflammatory processes in liver disease." (PMID 41168263, 2025).
Lyme disease (3 papers, 2013 to 2025). Lyme disease (named after the towns in the USA where the disease was first identified) is a bacterial infection caused by Borrelia burgdorferi. "Only patient 9, who also had Lyme antibodies in the CSF, was considered as having a Lyme disease with GFAP-Abs considered as an alternative diagnosis." (PMID 37540278, 2023).
malaria (3 papers, 2019 to 2025). Malaria is a serious and sometimes fatal disease caused by a parasite that commonly infects a certain type of mosquito which feeds on humans. "Notably, the individuals who have had past infectious/tropical diseases had lower GFAP, with Malaria driving this association." (PMID 41282064, 2025). "As few studies have reported paediatric UCH-L1, NF-L, and GFAP levels and none in malaria-endemic countries, the findings of this study need to be validated in larger, multi-site paediatric studies to establish reference ranges for these biomarkers." (PMID 38075948, 2023).
mental disorder (3 papers, 2022 to 2025). A disease that has its basis in the disruption of mental process. "Logistic regression revealed that craniocerebral injury severity, family satisfaction, and serum levels of S100-β and GFAP were significant risk factors for post-traumatic mental disorders (p < 0.05)." (PMID 39801405, 2025). "The diagnostic value of MMP-9, S100-β, and GFAP in detectingpost-traumatic mental disorders is substantial, with a significant correlationobserved among the biomarkers." (PMID 39801405, 2025). "Previous studies had suggested that NfL and GFAP could reflect neurodegeneration, and are associated with various neurodegenerative diseases, such as neuroinflammation, brain edema–induced diseases, traumatic brain injury, AD, and mental disorders." (PMID 40847451, 2025). "In this study, patients with post-traumatic mental disorders exhibitedsignificantly higher GFAP levels compared to those with simple craniocerebraltrauma." (PMID 39801405, 2025). "Serum levels of MMP-9, S100-β, and GFAP hold significant promise for thefuture diagnosis and management of post-traumatic mental disorders." (PMID 39801405, 2025). "GFAP is a signature protein of astrocytes, and its serum levels are closelyrelated to the development of post-traumatic mental disorders." (PMID 39801405, 2025). "Serum levels of MMP-9, S100-β, and GFAP were significantly elevated in the post-traumatic mental disorder group compared to the simple traumatic brain injury group (p < 0.001)." (PMID 39801405, 2025). "Spearman correlation analysis showed that serum MMP-9, S100-β and GFAP were significantly positively correlated with the incidence of post-traumatic mental disorders (p < 0.001)." (PMID 39801405, 2025). "Spearman correlation analysis of serum MMP-9, S100-β,GFAP, and the incidence of post-traumatic mental disorders." (PMID 39801405, 2025). "GFAP also plays arole in glial scar formation, which may disrupt neural circuit reconstruction andhinder functional recovery, contributing to mental disorders." (PMID 39801405, 2025). "Future efforts should focus on using a panel of GFAP and other blood and possibly genetic biomarkers, combined with imaging modalities, to improve prediction of the development of PTSD and related mental disorders following mTBI." (PMID 35717463, 2022).
mesenchymal tumors (3 papers, 2012 to 2024). "Absent reaction to S100, cytokeratin, SMA, desmin, muscle specific actin, smooth muscle myosin heavy chain, and GFAP is used to exclude other mesenchymal tumors." (PMID 25114687, 2014). "Pan-Cytokeratin (CK, an epithelial tumor cells marker), vimentin (a marker of mesenchymal tumor), α-actin (a marker of myogenic tumor), CD31 (a marker for vasculogenesis), NF-M and GFAP (markers of neurogenic tumor) were used to stain the tumors (data not shown)." (PMID 22511923, 2012). "IHC is used to differentiate gastric schwannoma from other GI mesenchymal tumors; gastric schwannoma strongly and diffusely stains positive for S100, vimentin, and glial fibrillary acidic protein (GFA) and is consistently negative for CD117, DOG -1, CD 34 and smooth muscle actin (SMA)." (PMID 39027743, 2024).
metabolic syndrome (3 papers, 2018 to 2025). A cluster of metabolic risk factors for CARDIOVASCULAR DISEASES and TYPE 2 DIABETES MELLITUS. "MCAO significantly enhanced GFAP-positive cell in CA1 and CA2 metabolic syndrome rats (P value < 0.05 and 0.01, respectively, compared to the HCHF+sham operation+vehicle group)." (PMID 30937145, 2019). "An increase in hypothalamic GFAP and TNF-α in our study suggests that an obesogenic diet induces a shift in astrocytes towards astrogliosis, characterized by the production of inflammatory cytokines, regardless of the severity of the metabolic syndrome-like phenotype." (PMID 41305664, 2025).
metachromatic leukodystrophy (3 papers, 2024 to 2025). A rare lysosomal storage disorder characterized by intralysosomal accumulation of sulfatides in various tissues, leading to progressive deterioration of motor and neurocognitive function. "Recently, Beerepoot and colleagues showed elevations in both GFAP and NfL in metachromatic leukodystrophy, although the degree of increase for GFAP was less than that seen in AxD." (PMID 38558318, 2024).
Myoepithelial carcinoma (3 papers, 2023 to 2025). "Myoepithelial carcinoma usually stains positive for high molecular weight cytokeratins (AE1/AE3, KRT14) and myoepithelial markers, such as smooth muscle actin (SMA), p63, S100, GFAP, and calponin." (PMID 37705036, 2023).
narcolepsy (3 papers, 2018 to 2024). A sleep disorder characterized by a tendency for excessive sleepiness during the day which occurs even after adequate sleep in the nighttime. "In narcolepsy of PD patients elevated levels of glial fibrillary acidic protein (GFAP) in the CSF seem to be causative for the reduction of orexin levels pointing to GFAP as another potential biomarker." (PMID 30214392, 2018). "Here, glial fibrillary acidic protein (GFAP) levels, suggestive of neuroinflammation, were reported as significantly higher in patients with hypersomnolence and narcolepsy, but not in patient with PD without hypersomnolence." (PMID 39031323, 2024).
neuroepithelial tumors (3 papers, 2013 to 2025). "Negative GFAP and S-100 help exclude neuroepithelial tumors." (PMID 41246661, 2025).
neuronal ceroid lipofuscinosis (3 papers, 2016 to 2025). "We demonstrate that GFAP palmitoylation is regulated by PPT1, a palmitoylprotein thioesterase linked to a childhood neurodegenerative disorder, infantile neuronal ceroid lipofuscinosis." (PMID 33753498, 2021). "In an infantile neuronal ceroid lipofuscinosis (INCL) mouse model, malfunctioning of palmitoyl thioesterases resulted in the increased palmitoylation of GFAP at the cysteine-291 residues." (PMID 41002922, 2025).
neurosarcoidosis (3 papers, 2021 to 2025). A sarcoidosis that involves the nervous system. "Compared to neurosarcoidosis patients, the CSF of GFAP‐IgG‐positive patients had higher concentrations of IL5 (P = 0.001) and lower concentrations of GM‐CSF and IFN‐gamma (P < 0.01 for each)." (PMID 39869499, 2025). "As for the perivascular radial contrast-enhancement pattern involving the supratentorial white matter seen in anti-GFAP AE, it is worth remembering that a similar finding can be seen in neurosarcoidosis and sometimes in lymphomatoid granulomatosis (LYG)." (PMID 38507081, 2024).
oligodendroglial tumor (3 papers, 2012 to 2020). Oligodendrogliomas are cerebral tumors that are differentiated from other gliomas on the basis of their unique genetic characteristics and better response to chemotherapy. "In oligodendroglial tumors, reactive astrocytes were distinguishable from mIDH1R132H-positive and GFAP-negative tumor cells based on their GFAP expression in the cytoplasm and lack of mIDH1R132H immunoreactivity." (PMID 32599896, 2020). "Also in a subset of patients with oligodendroglial tumors, high levels of GFAP were found in plasma, implying that circulating GFAP is not specific for high-grade malignant astrocytic neoplasms." (PMID 25720744, 2015).
osteoarthritis (3 papers, 2011 to 2013). A noninflammatory degenerative joint disease occurring chiefly in older persons, characterized by degeneration of the articular cartilage, hypertrophy of bone at the margins and changes in the synovial membrane. "RA patients revealed an increase in the expression of GFAP and A1BG in the plasma as compared to osteoarthritis patients." (PMID 23418544, 2013).
Papillary Meningioma (3 papers, 2015 to 2021). A WHO grade III meningioma characterized by the predominance of a perivascular pseudopapillary pattern. "More recently GFAP immunopositivity has been recognized in other types of neoplastic and normal tissues as well, including epiglottic cartilage, renal carcinoma metastatic to brain, malignant pleomorphic adenoma of the salivary glands, and papillary meningioma." (PMID 26155457, 2015). "The distinction between astroblastomas and nonglial papillary tumors such as papillary meningiomas and metastases from papillary tumors is aided by immunohistochemical features that show positive staining with glial markers such as GFAP and S-100." (PMID 29678196, 2018).
primary central nervous system lymphoma (3 papers, 2022 to 2025). A non-Hodgkin or Hodgkin lymphoma that arises in the brain or spinal cord as a primary lesion. "We reported a case of primary central nervous system lymphoma (PCNSL) coexistent with glial fibrillary acidic protein (GFAP) astrocytopathy, and discussed the problems needing attention in the diagnosis and differential diagnosis of GFAP astrocytopathy." (PMID 35153997, 2022).
primitive neuroectodermal tumor (3 papers, 2009 to 2021). A malignant neoplasm that originates in the neuroectoderm.
retinopathy of prematurity (3 papers, 2019 to 2024). A bilateral retinopathy characterized by neovascularization, scarring, retinal detachment, and eventually blindness. "Serum NfL and GFAP levels, retinopathy of prematurity (ROP), intraventricular hemorrhage, and Bayley Scales of Infant Development II and III at 2 years of age, analyzed by multivariate logistic regression measured by odds ratio (OR), and receiver operating characteristic curve (ROC) analysis." (PMID 33797551, 2021).
sleep disorder (3 papers, 2024 to 2025). A change from the patient's baseline sleeping pattern, in the hours slept and/or an alteration/dysfunction in the stages of sleep. "In contrast, serum GFAP levels may increase in individuals experiencing sleep disorders, such as insomnia." (PMID 39770491, 2024). "Additionally, we found that APOE ε4 carriers with sleep disorder had the highest plasma NfL and GFAP compared to the other groups." (PMID 38421124, 2024). "Some studies revealed the potential utilization of neurofilament light chain (NfL) and glial fibrillary acidic protein (GFAP) concentration levels as biomarkers of sleep disorder and daytime drowsiness, as well as their roles in predicting decline in neurodegeneration and cognitive performance." (PMID 38421124, 2024). "Only one clinical study showed elevated GFAP levels as an indicator of disrupted sleep and sleep‐related disorders in individuals at risk for AD—in particular, for APOE ε4 carriers with sleep disorder who had the highest plasma GFAP compared to non-carriers with or without sleep disorder." (PMID 40690136, 2025).
spina bifida (3 papers, 2013 to 2022). A congenital neural tube defect in which vertebrae are not fully formed. "In our study, we noticed that GFAP expression in the radial glia and roof plate area, as well as stronger pgp expression in the roof area of abnormal fetus with spina bifida were associated with increased sr expression, particularly sr3." (PMID 34298938, 2021). "Indeed, we demonstrated changes in astrogenesis in spinal cords of fetuses with spina bifida with the presence of differentiated (GFAP) astroglial cells as early as E15 that progressively increase throughout the rest of gestation." (PMID 35782393, 2022). "Altered cell quantification of astrocytes (GFAP) and neurons (NeuN) expression has been described in spina bifida in utero, but the correlation with the NPC which are the origin of these differentiated cell types it is not understood in spina bifida physiopathology." (PMID 35782393, 2022).
spindle cell tumors (3 papers, 2022 to 2024). "This study shows that most facial spindle cell tumors were compatible with peripheral nerve sheath tumors (PNSTs) based on positive immunohistochemical staining for Sox10 and other immunohistochemical markers such as GFAP, NSE, and S100." (PMID 38612342, 2024). "Although GFAP is expressed in only a small percentage of MNSTs, we believe that it may still be useful in some cases to distinguish NSTs arising outside the CNS from other spindle cell tumors." (PMID 35622732, 2022). "Histology of the peripheral parts of the lesion demonstrated a cellular spindle cell tumor with central degeneration, positive for SOX10, S100 and GFAP." (PMID 37535242, 2023).
thyroid (3 papers, 2013 to 2022). "Quantitative analysis of the immunofluorescence intensity showed that the NaIO3 treatment increased expression of GFAP by about 67%, compared with untreated controls, and treatment with anti-thyroid drug completely abolished the NaIO3-induced GFAP expression." (PMID 31932580, 2020).